HHLA1 (HHLA1 neighbor of OC90)
Synonyms: PLA2L
Tractability: Antibody: UniProt places it where antibodies can reach, with high confidence; UniProt predicts a signal peptide or a membrane-spanning region; its Gene Ontology location is reachable by antibodies, with medium confidence.
Gene: Protein-coding gene on chromosome 8 (132,061,480 to 132,111,159, reverse strand). Ensembl gene ENSG00000132297.
Subcellular location: Secreted
Gene Ontology:
Cellular component: extracellular region
Genetic constraint (gnomAD): Loss-of-function variants: 39 observed, 40.82 expected, observed/expected ratio (o/e) 0.96, 90% interval 0.74 to 1.25. The upper end of that interval is the gene's LOEUF score, 1.25, which puts it in group 5 of 6, group 1 being the genes least tolerant of losing a copy. Missense variants: 490 observed, 464.53 expected, observed/expected ratio (o/e) 1.05, 90% interval 0.98 to 1.14. Synonymous variants: 173 observed, 168.62 expected, observed/expected ratio (o/e) 1.03, 90% interval 0.91 to 1.16.
Homologues: Orthologues: chimpanzee HHLA1 (90% identical), macaque HHLA1 (86% identical), dog HHLA1 (73% identical), rat Hhla1 (61% identical), mouse Hhla1 (60% identical), pig HHLA1 (60% identical).
Diseases named in the same sentence as HHLA1 in open-access papers:
HHLA1 is named in the same sentence as 5 diseases in open-access papers, as found by Europe PMC text mining. Sharing a sentence is not in itself a finding about the gene and the disease. The quoted sentences say what the papers report.
metastatic tumors (1 paper, 2017). "Chromosomal gains at MECOM and HHLA1 loci suggest that the observed cells were cancer cells and reflect pathophysiological decisive chromosomal aberrations of the primary and metastatic tumors." (PMID 29290959, 2017).
ovarian carcinoma (1 paper, 2017). A malignant neoplasm originating from the surface ovarian epithelium. "Our data suggest that CTCs detected by the multi-marker protein panel and/or MECOM/HHLA1 FISH represent minimal residual disease in optimally debulked ovarian cancer patients." (PMID 29290959, 2017).
tumor (2 papers, 2017 to 2023). "At the genome level, gains in the MECOM and HHLA1 loci were observed in the primary tumor and the metastases, as well as in just 25% and 50% of the CK7/18-positive CTCs, respectively." (PMID 29290959, 2017). "A multi-marker immunostaining was established and further complemented by FISH on CTCs and tumor/metastasis tissues using probes for stem-cell like fusion genes MECOM and HHLA1." (PMID 29290959, 2017).
cancer (1 paper, 2017). A tumor composed of atypical neoplastic, often pleomorphic cells that invade other tissues. "Likewise, it has been demonstrated that aberrations in the chromosomal region 8q24.21-8q24.22 comprising the HHLA1 locus occurred frequently in these cancers." (PMID 29290959, 2017). "In addition to immune-fluorescent staining of CTCs, we performed fluorescence in situ hybridization (FISH) in some selected cases to investigate the copy number of the stem-cell like fusion genes MECOM/HHLA1 and to pinpoint CTCs as cancer cells in case of doubt." (PMID 29290959, 2017). "The presence of MECOM and/or HHLA1 gains in all CTC samples investigated confirmed the specificity of the multi-marker staining, and furthermore allowed us to ascertain that “ambiguous” cells corresponded to cancer cells, thus enabling us to extend the CTC count." (PMID 29290959, 2017).
HHLA1 also shares sentences with these, for which no sentence is quoted: teratocarcinoma (1 paper).